BRAF (B-Raf proto-oncogene, serine/threonine kinase)
Diseases named in the same sentence as BRAF in open-access papers (continued):
Sharing a sentence is not in itself a finding about the gene and the disease.
melanoma (continued). "SEMA6A levels progressively increased, suggesting that SEMA6A may have prognostic relevance in BRAF-mut melanoma." (PMID 35440004, 2022). "Several studies have shown that targeting various molecular alterations of interest in specific tumor types can improve outcomes, including EGFR, ALK, ROS1 or BRAF V600E in non-small-cell lung cancer, BRAF V600E in melanoma, BCR-ABL in chronic myeloid leukemia, or RET in medullary thyroid cancer." (PMID 35323355, 2022). "Additionally, it is important to remember that BRAF (V600E) ctDNA can be positive in plasma in other malignancies as well such as melanoma, lung cancer, and colorectal cancer." (PMID 34475951, 2021). "In addition, dual BRAF/MEK inhibition further decreased the production of immunosuppressive adenosine in BRAF mutant melanoma cells by reducing the expression of components within the CD73 adenosinergic pathway." (PMID 33807608, 2021). "In order to investigate three-drug vertical inhibition of the BRAF-MEK-ERK pathway in BRAFV600E-mutant melanoma, the model could directly be extended to include the effects of an ERK inhibitor." (PMID 34621046, 2021). "We next investigated whether combined treatment of BRAF inhibitor (dabrafenib) or MEK inhibitor (trametinib) with CRISPR-Olig2 could be effective in reducing melanoma cell viability." (PMID 33833342, 2021). "The EGFR/SFK pathway was found to mediate resistance to vemurafenib treatment in BRAF-mutant melanoma, and BRAF and EGFR/SFK inhibition was reported to block the proliferation and invasion of these tumors, providing potentially effective therapeutic options for these patients." (PMID 33474634, 2021). "Moreover, melanoma cells resistant to BRAF inhibitors (BRAFi) were unusually sensitive to inhibitors targeting NAMPT, which caused decreased cellular NAD levels." (PMID 34068679, 2021). "Two slow-growing UM cell lines XMP46 and MM28 (GNAQ/11-mutation, BAP1-negative) were not sensitive to VP, and neither were the two conjunctival melanoma cell lines (BRAF/NRAS-mutation)." (PMID 33798262, 2021). "The most common genetic aberration – BRAF V600E is a target of anti-melanoma therapy." (PMID 34702444, 2021). "However, they did not observe any specific differentially expressed miRNAs between BRAF- and NRAS-mutated melanomas." (PMID 34123788, 2021). "BRAF mutations occur more frequently in young people, in no-chronical ultraviolet (UV) exposure and are more aggressive compared to wild type melanomas." (PMID 34207514, 2021). "Similarly, an immunomodulatory effect of dasatinib on T cells has been associated with improved anti-tumor immunity, and BRAF/MEK inhibition in patients with melanoma leads to upregulation of TCF7 and expansion of melanoma-specific TIL." (PMID 33795428, 2021). "Therefore, USP28 depletion increased BRAF protein levels and melanoma cell resistance to BRAF inhibitors." (PMID 33800394, 2021). "Interestingly, it has also been shown that glutamine deficiency observed in core regions of melanoma xenografts drives H3K27 methylation, which results in cancer cell resistance to BRAF inhibitors." (PMID 33803675, 2021). "In melanoma, the Phosphoinositide 3-kinase (PI3K)/AKT pathway is implicated in mutations in phosphatase and tensin homologue (PTEN) and NRAS, which occur most frequently after BRAF mutations." (PMID 33833342, 2021). "About half of the melanoma patients harbor activating mutation in oncogenes involved in the mitogen-activated protein kinase (MAPK) pathway, e.g., BRAF or NRAS and/or constitutive activation of the cell cycle modulating phosphoinositide 3-kinase (PI3K) signaling pathway." (PMID 33578810, 2021). "BRAF inhibitor vemurafenib has been shown to upregulate MHC in BRAFV600E homozygous melanoma." (PMID 33807608, 2021). "While BRAF mutations have not previously been associated with rapid progression, increased rates of BRAF mutation in melanoma patients were observed in non-responders to immunotherapy compared to responders." (PMID 34202352, 2021).
melanoma (continued). "As for the treatments of melanoma, over the past decades, the management of melanoma has rapidly developed with the introduction of novel drug classes, such as BRAF and MEK pathway-targeted inhibitors and targeting immune check-point inhibitors consisting of CTLA-4, PD-1, PD-L1, and PD-L2." (PMID 33688507, 2021). "Combination or sequential therapies targeting metabolism in melanoma can help counter BRAF inhibitor resistance in melanoma, preventing the re-activation of BRAF downstream effectors or countering the shift towards oxidative phosphorylation associated with BRAF inhibition." (PMID 34831420, 2021). "The ability to combine the fast and frequent response to BRAFi with the long-term efficacy of immunotherapy might dramatically change the natural history of BRAF-mutant melanoma." (PMID 34210820, 2021). "Furthermore, BRAF‐V600E is found in 50% of melanoma, and it is estimated that about a third of these cancers arise from a pre‐existing nevus." (PMID 34355491, 2021). "In addition to melanoma-associated mutations such as BRAF, NRAS, PTEN and cell cycle regulators, the expansion of melanoma is affected by the extracellular matrix surrounding the tumor together with immune cells." (PMID 35127523, 2021). "The BRAF-mutant human cancers, e.g., melanomas, show a good response to BRAF-targeted inhibition." (PMID 35048058, 2021). "BRAF mutations are generally not V600E; the BRAF V600K mutation was significantly associated with older age, male sex, head and neck primary melanoma site, a higher degree of chronic sun damage, and short overall survival." (PMID 34440462, 2021). "Moreover, there are pieces of evidence of potential synergy between XPO1 and BRAF inhibition in BRAF-mutant melanoma, but this needs to be further investigated in a clinical setting." (PMID 34575598, 2021). "The combination of BRAF/MEK inhibitors shows the highest response rates of all melanoma therapies." (PMID 33993415, 2021). "Notably, JARID1B was recently identified as a marker of cross-resistance in melanoma cells treated with BRAF inhibitors and radiation." (PMID 33800547, 2021). "Pharmacological BRAF inhibition is an established treatment for BRAFV600E-positive melanoma." (PMID 33947959, 2021). "Additionally, in melanoma, LOXL3 maintains genomic stability through an association with oncogenic BRAF and promotes sustained proliferation." (PMID 34360836, 2021). "BRAF/MEK combined therapy has become a standard option for patients with BRAF V600-mutant melanoma." (PMID 34064013, 2021). "BRAF, NRAS and c-KIT mutations in melanoma have shown to be distinct clinic-pathological entities." (PMID 34572865, 2021). "Moreover, a KDM6B deficiency with a subsequent H3K27me3 enrichment promoted the dedifferentiation of hypoxicV600E BRAF melanoma cells and then led to BRAF inhibitor resistance." (PMID 33414463, 2021). "Most patients with completely resected stage III BRAF-mt cutaneous melanoma are candidates for any of the three different adjuvant treatments, whereas patients with completely resected stage III BRAF wild-type melanoma are only candidates for adjuvant treatment with pembrolizumab or nivolumab." (PMID 34781194, 2021). "The phase III trials BRIM-3 and BREAK-3 compared BRAF inhibitors to dacarbazine in patients with previously untreated stage IV or unresectable stage III BRAF V600E-positive melanoma, showing a BRAF inhibitor improves response rates, PFS, and OS compared with chemotherapy alone." (PMID 34885172, 2021). "BRAF oncogene plays a key role in the metabolic reprogramming of melanoma cells." (PMID 34073463, 2021). "Thus, therapeutics that inhibit BRAF and evade these mechanisms of resistance have gained significant interest as potential treatments of melanoma." (PMID 33807778, 2021).
melanoma (continued). "We did not observe a correlation between MITF expression and the most common BRAF, NRAS, and NF1 mutations found in melanoma, indicating that the gene expression changes observed are controlled via transcriptional regulation, directly or indirectly imposed by MITF." (PMID 33438577, 2021). "Additionally, melanoma cell lines and tumor models that are resistant to the BRAF inhibitor vemurafenib exhibit reactivated MAPK signaling and upregulated cyclin D1, and are sensitive to abemaciclib treatment." (PMID 33806615, 2021). "Furthermore, elevated levels of protein p63 were described in melanoma cells exposed to BRAF and MEK inhibitors." (PMID 34063141, 2021). "KEYNOTE-002 study was a randomized phase II multicenter trial in which advanced melanoma patients with progression after ipilimumab and/or BRAF/MEK inhibitors were randomized to pembrolizumab 2 mg/kg or 10 mg/kg every 3 weeks or investigator-choice chemotherapy." (PMID 34447613, 2021). "ICIs, given as monotherapy or in combination, are now first line treatments for wild-type (non-BRAF mutant) melanoma in the adjuvant and metastatic settings, offering tremendous hope and often durable responses in some patients refractory to other forms of therapy." (PMID 33810078, 2021). "Moreover, with accumulating data on non-melanoma BRAF-driven cancers, it is expected that the number of clinical trials testing co-targeting of autophagy plus RAF > MEK > ERK signaling will expand in the near future." (PMID 34298710, 2021). "Results from another randomized, double-blind, phase III trial revealed that nivolumab significantly improved the overall survival rate of patients with advanced melanoma without BRAF mutations, relative to dacarbazine." (PMID 34125407, 2021). "Further, we obtained two melanoma-derived cell lines resistant to BRAF inhibitor vemurafenib." (PMID 34680379, 2021). "Hence, the effects of combined BRAF/MEK inhibition in melanoma patients on immune responses should be synergistic or at least additive, thereby explaining the reported clinical benefits by combining immune checkpoint blocking antibodies with targeted therapy." (PMID 33275172, 2021). "Collectively, our study demonstrated that miR-181a/b could reverse the resistance to BRAF inhibitors in dabrafenib resistant melanoma cell lines." (PMID 33670365, 2021). "Combined inhibition of BRAF/MEK is an established therapy for melanoma." (PMID 33275172, 2021). "Since 80% of human cutaneous melanomas harbor activating hot-spot mutations in either BRAF or NRAS (e.g., BRAFV600, NRASG12, or NRASQ61), we examined the nf1/pten-mutant zebrafish melanomas for spontaneous mutations at equivalent sites in the zebrafish orthologues." (PMID 34331013, 2021). "Besides, Ocoxin interferes with the cell cycle, impairs the inherent and fibroblast-mediated melanoma cell migration, and reduces resistance to BRAF inhibition." (PMID 33669949, 2021). "Unlike most common and congenital nevi and malignant melanomas, they lack oncogenic BRAF and NRAS mutations and harbor tumorigenic HRAS mutations or kinase gene fusions involving ALK, BRAF, MET, NTRK1, NTRK3, RET, and ROS1 in a mutually exclusive pattern." (PMID 34830218, 2021). "Our analysis revealed improvements in median OS for patients with the successive introduction of novel therapies for all melanoma patients, patients with BRAF mutant melanoma, and for patients with BRAF wild-type or unknown melanoma." (PMID 34677256, 2021). "In this context, it could be interesting to study the effect of the combination of CRO15 or other MELK inhibitors and BRAF inhibitors for melanoma treatment." (PMID 33431809, 2021). "YAP and TAZ expression was demonstrated to be enhanced in BRAF inhibitor-treated melanoma cells." (PMID 34066022, 2021). "In this regard, these molecules could be used in the clinic together with BRAF inhibitors to address melanoma resistance." (PMID 34827551, 2021).
melanoma (continued). "Furthermore, we demonstrate correlation between BRAF V600E mutant allele frequency and clinical disease status in two patients with known BRAF V600E mutant melanoma." (PMID 33799709, 2021). "We compared melanomas with BRAF mutational resistance mechanisms (BRAF splicing and amplification) to melanomas lacking known mutations that drive resistance." (PMID 34503064, 2021). "Conversely, while the vast majority of patients with BRAF-mutant melanoma has objective responses or temporary stable disease when treated with a BRAF inhibitor, they inevitably relapse, almost always in the first 1–2 years of therapy due to acquired resistance." (PMID 34713141, 2021). "Hence, by regulating glycolysis, CHD4 silencing or PAD1 and PAD3 expression acts to modulate melanoma cell sensitivity to BRAF inhibition." (PMID 33741961, 2021). "It has been reported that previous treatment with BRAFi with or without MEKi result in shorter survival in BRAF-mutated melanoma patients when treated with anti-PD-1 antibody." (PMID 35069558, 2021). "We hypothesize that this preresistant state may constitute a basin within a BRAF mutant melanoma epigenetic landscape, similar to our single cell-derived sublines (DS3, DS6, DS7, and DS9) that we contend occupy the PC9-VU epigenetic landscape." (PMID 34061819, 2021). "Preclinical studies in melanoma have also revealed that combined BRAF and MEK inhibition induces cancer cell death via pyroptosis – a highly inflammatory form of programed cell death, which triggers an anti-tumor immune response that persists even after drug treatment is completed." (PMID 34277419, 2021). "For patients with BRAFV600E/K mutant melanoma the first line treatment is generally a BRAF/MEK inhibitor, and upon progression patients may receive IO therapy as 2nd line treatment." (PMID 34301276, 2021). "Although BRAF is the most frequently mutated driver gene in melanoma, BRAF mutations alone are nevertheless not sufficient for melanoma development." (PMID 34063141, 2021). "We further examined whether combined inhibition of mutant BRAF and DUBs would co-operate to reduce tumor burden in xenograft models of melanoma." (PMID 33613844, 2021). "We identified the mature microRNAs that are specifically altered in BRAF (V600E) melanoma." (PMID 34698264, 2021). "Similarly, expression of a BRAF (B-Raf proto-oncogene) isoform that lacks the RAS binding domain promotes resistance to BRAF inhibition in a group of melanoma patients." (PMID 34961772, 2021). "To validate the 18 candidate regulators of the molecular networks underlying primary melanoma prognosis, we performed siRNA knockdown experiments in SKmel147 (NRAS mutant) and A375 (BRAF mutant) cell lines (see siRNA screening of candidate targets in Supplementary Methods)." (PMID 33619278, 2021). "We observed that six of the nine UVR mucosal melanomas carried BRAF mutations, whereas only one of the nine non-UVR mucosal melanomas had a BRAF mutation." (PMID 33431815, 2021). "Mutations in the BRAF gene could cause an impaired protein function, and BRAFV600 mutations have been detected in nearly 50% of malignant melanoma and activate the downstream pathway of MAPK." (PMID 34069297, 2021). "Altogether, these genetic alterations influence clinical decisions for metastatic disease management with BRAF and MEK inhibitor treatment being suitable for patients with BRAF-mutated melanomas, while patients with KIT-mutated melanomas benefit from KIT inhibitors." (PMID 34359736, 2021). "Thus, inhibition of MELK in combination with BRAF inhibitors allows for an effect on resistant melanoma cell viability compared to BRAF inhibitors alone and decreases the development of resistance." (PMID 33431809, 2021). "Mutated CRAF was shown to be a rare driver oncogene overexpressed in BRAF or NRAS melanoma cells." (PMID 34063141, 2021).
melanoma (continued). "Furthermore, PD-L1 expression is also induced by YAP in BRAF inhibitor-resistant melanoma, and the relationship between YAP and PD-L1 expression was validated in human clinical melanoma tissues." (PMID 34395269, 2021). "Furthermore, downregulation of a protein encoding gene, DUSP4, has been shown to contribute to MEK resistance in BRAF wild-type melanoma." (PMID 33807778, 2021). "Despite the presence of multiple melanocytic nevi (MNs), CFC-associated BRAF variants do not increase the incidence of melanoma or cSCCs." (PMID 33800195, 2021). "Current clinical studies are investigating new therapy options for melanoma patients with brain metastases such as PD-1 antibodies, ipilimumab plus nivolumab, BRAF inhibitors plus MEK inhibitors, as well as stereotactic radiotherapy in combination with immunotherapy or targeted therapy." (PMID 33993415, 2021). "BRAF-resistant melanomas usually determine a reactivation of the MAPK signaling pathway." (PMID 34178657, 2021). "In a study investigating the prognostic and predictive values of oncogenic BRAF, NRAS, c-KIT, and MITF in melanoma, it was found that initial lymph node involvement was more frequent in patients with BRAF-mutated melanomas, than in cases presenting other mutations." (PMID 34209415, 2021). "However, real-world data on treatment patterns and clinical outcomes for patients with advanced BRAF V600 mutant melanoma are ultimately scarce." (PMID 34064013, 2021). "The sensitivity of melanoma cells to chloroquine was shown as independent of the BRAF mutation status." (PMID 33916175, 2021). "Overall, HA15 exhibits strong anti-cancer effects in prostate, breast, colon, pancreas, glioma, cervical, and melanoma cells regardless of driver mutations or BRAF inhibitor resistance." (PMID 33498201, 2021). "CAFs in BRAF mutant melanoma may participate in resistance to BRAF inhibitor PLX4720 by generating fibronectin-rich matrix." (PMID 34095111, 2021). "The development and progression of superficial spreading melanoma, which is common in Caucasoid patients, is correlated with UV exposure, which can cause genetic mutations, such as BRAF and NRAS mutations, which lead to the development and progression of malignant melanoma." (PMID 34207144, 2021). "The outcomes from this analysis support the use of pembrolizumab as a first-line treatment of advanced melanoma regardless of its BRAF V600E/K mutation status." (PMID 34885172, 2021). "In addition, for those with BRAF-mutant melanoma tumors, targeted therapy alone has led to survival improvements; however, this is not curative." (PMID 34187852, 2021). "Genomic biomarkers paired with targeted therapies have proven highly efficacious in some cases, such as HER2 amplification and trastuzumab in breast cancer, BRAF mutation and combined BRAF/MEK inhibition in melanoma and EML4-ALK fusions and Crizotinib in lung adenocarcinoma." (PMID 34680271, 2021). "BRAF fusions in mucosal melanomas have also been described, with a comparable frequency as of cutaneous triple wild type melanoma (i.e., lacking BRAF, NRAS, and NF1 mutations)." (PMID 35008570, 2021). "Although BRAF inhibitors have been practice-changing in the treatment of BRAF-mutated melanoma, they demonstrated a surprising and striking lack of efficacy as single agents in patients with colorectal cancer harboring BRAFV600E mutations." (PMID 34299337, 2021). "The main oncogenic driver mutations in cutaneous MM are the BRAF (serin/threonine protein kinase) and NRAS (neuroblastoma RAS viral oncogene) mutations, whereas KIT (tyrosine-protein kinase) mutations are predominantly observed in mucosal and acral melanomas." (PMID 33562484, 2021). "While triple therapy combinations were prone to a higher incidence of AEs, these studies were the first to indicate that BRAFi/MEKi/anti-PD1/PDL1 combinations have the potential to increase the frequency of long-lasting antitumor responses in BRAF v600-mutant melanoma patients." (PMID 33925915, 2021).